IL19 (interleukin 19)
Diseases named in the same sentence as IL19 in open-access papers (continued):
Sharing a sentence is not in itself a finding about the gene and the disease.
Anxiety (1 paper, 2023). Intense feelings of nervousness, tension, or panic often arise in response to interpersonal stresses. "Certain literature has shown that endotoxins and stress-induced anxiety can enhance the expression of IL-19, while β-adrenergic receptor antagonists can block the stress-induced increase in IL-19 expression." (PMID 36936941, 2023). "In conclusion, IL-19 plays an essential role in comorbidities related to IBD and anxiety, which can not only control colonic inflammation through the activation of STAT3 but also cause anxiety by down-regulating the ERK-CREB-BDNF pathway." (PMID 36936941, 2023). "The ongoing correlation analysis indicated that mRNA levels of IL-19 positively correlated with anxiety-related behaviors but not depressive behaviors regarding the sucrose preference test in the DSS/CUS group." (PMID 36936941, 2023). "IL-19 and its receptor may be important in designing therapeutic agents for comorbidities related to IBD and anxiety." (PMID 36936941, 2023). "Then, we measured the anxiety-related behaviors and the symptoms of IBD after overexpression of IL-19 in colon; furthermore, we evaluated how IL-19 affects the sensitivity of the DSS/CUS-induced comorbid anxious behaviors; the pathological severities and their molecular pathways were determined." (PMID 36936941, 2023).
autoimmune encephalitis (1 paper, 2021). Inflammation of the brain secondary to an immune response triggered by the body itself. "In fact, we recently showed that IL-19 deficiency worsened microglia/macrophage-mediated experimental autoimmune encephalitis, whereas IL-19 treatment abrogated this condition by inhibiting macrophage activation." (PMID 33931083, 2021).
autoimmune gastritis (1 paper, 2022). Inflammation of the body fundic mucosa of the stomach. "On the basis of results obtained at serum level, we then asked whether IL-19 is produced in vivo by patients with PA and autoimmune gastritis." (PMID 35479078, 2022). "We compared serum levels of IL-19, IL-20, IL-26, IL-28A and IL-29 in 43 patients with PA and autoimmune gastritis, in 20 patients with IDA and no autoimmune gastritis, and in 47 HC." (PMID 35479078, 2022). "Thus, we suggest that serum levels of IL-19 may represent a novel important tool to discriminate PA with autoimmune gastritis from IDA without autoimmune gastritis and that the measurement of serum IL-19 might be useful for monitoring the response to B12 vitamin therapy in PA patients." (PMID 35479078, 2022).
autoimmune myocarditis (1 paper, 2021). Autoimmune myocarditis is an autoimmune disease that affects the heart. "For example, IL-19 gene recombinant plasmid was used to treat experimental autoimmune myocarditis in rats." (PMID 34671659, 2021).
Behçet’s disease (1 paper, 2025). "Furthermore, these patients also show elevated levels of IL-19, another cytokine in the IL-10 family, compared to those with Behçet’s disease, sarcoidosis, and VKH disease." (PMID 40433375, 2025).
brain tumors (1 paper, 2025). "MRI imaging demonstrated enhanced targeting efficiency in brain tumors, with in vivo studies showing prominent hypointense areas in T2*-weighted MRI scans of tumor-bearing mice injected with CHOL-PEG-SPIO-IL-19, highlighting nanoparticle presence in IL-19-expressing regions." (PMID 40057744, 2025).
chronic asthma (1 paper, 2019). An asthma that is characterized by the development of persistent airway inflammation and recurrent attacks of breathlessness and wheezing, which vary in severity and frequency. "To further confirm whether direct inhibition of IL-19 would attenuate chronic asthma Der p-treated mice, we treated mice with mIL-19 neutralizing antibodies." (PMID 31114590, 2019). "To verify the role of IL-20R1-mediated IL-19 signaling in the development of allergic lung inflammation, we compared the pathological outcomes between WT and IL-20R1−/− mice in the Der p-induced chronic asthma model." (PMID 31114590, 2019). "We also examined whether inhibiting IL-19 and IL-20R1 ameliorated Der p-induced chronic asthma." (PMID 31114590, 2019).
chronic hepatitis B infection (1 paper, 2021). "Moreover, it has been shown that some polymorphism in IL-19 and IL-20 genes could worsen the outcome of chronic hepatitis B infection and septic shock." (PMID 34944654, 2021).
chronic kidney disease (1 paper, 2020). Impairment of the renal function secondary to chronic kidney damage persisting for three or more months. "We also demonstrated the increased production of Il19, Il20, and Il24 in the kidney samples from the different animal models of acute and chronic kidney disease." (PMID 32306980, 2020).
diabetic foot ulcers (1 paper, 2023). "Specifically, monocytes/macrophages increased expression of several apoptosis genes (including BCL2, FGFR3, FGFR1, CTH, CASP3, IL19, NME5, and S100A8/9) in diabetic foot ulcers compared to monocytes/macrophages in non-diabetic wounds." (PMID 38127424, 2023).
disc degeneration (1 paper, 2018). "However, it is not clear whether IL-19 is also more potent than IL-20 in vivo for disc degeneration." (PMID 30250404, 2018).
ductal carcinoma (1 paper, 2022). "Individuals with ductal carcinoma recorded significant differences (p<0.001) in the mean levels of the interleukin-19 and TNF-α compared with healthy groups." (PMID 35928364, 2022). "Additionally, BCP with ductal carcinoma showed significant differences in the mean levels of IL-19 and TNF-α in comparison with healthy people." (PMID 35928364, 2022).
experimental autoimmune encephalomyelitis (1 paper, 2021). An autoimmune demyelinating disease of the central nervous system that is produced experimentally in animals by the injection of homogenized brain or spinal cord in Freund's adjuvant. "Here, we demonstrate that IL-19 deficiency aggravates experimental autoimmune encephalomyelitis (EAE), a mouse model of MS, by promoting IL-17-producing helper T cell (Th17 cell) infiltration into the CNS." (PMID 33776998, 2021).
fungal infection (1 paper, 2024). "M-CSF, IL-1α and IL-19 concentration in the hemolymph after fungal infection, and significantly lower TNF-β and G-CSF." (PMID 38774871, 2024).
hematoma (1 paper, 2021). A hematoma is a collection of blood from a vascular structure into an extravascular space. "The purpose of this study is to investigate interleukin-19's role in hematoma clearance after GMH and its underlying mechanism of IL-20R1/ERK/Nrf2 signaling pathway." (PMID 33532035, 2021). "IL-19 activation of ERK and its downstream protein Nrf2 play a pivotal role in the expression of CD163 and its enhancement of hematoma clearance after GMH." (PMID 33532035, 2021).
hepatoma (1 paper, 2013). "To determine whether IL-19 promotes the expression of TNF-α and IL-10, we analyzed the effect of IL-19 on the HepG2 human hepatoma cell line." (PMID 23468852, 2013). "In the subsequent in vitro studies, IL-19 raised the level of TNF-α and IL-10 transcripts in hepatoma cells, which may cause liver inflammation and lead to hepatic damage." (PMID 23468852, 2013). "However, unlike M1 cells, IL-19 did not induce IL-19 transcripts in hepatoma cells and lung epithelial cells, which suggests that there is no auto-induction in the liver or lungs." (PMID 23468852, 2013).
Hepatomegaly (1 paper, 2023). Abnormally increased size of the liver. "Pretherapy IL-19 levels were significantly associated with both hepatomegaly and splenomegaly." (PMID 36726488, 2023).
Hyperglycemia (1 paper, 2017). An increased concentration of glucose in the blood. "This study is in agreement with the previous studies, which have suggested that hyperglycemia is the driving force for the development of DN.We also showed a positive correlation between IL-19 concentration and HbA1c." (PMID 28201997, 2017).
Hypertension (1 paper, 2017). The presence of chronic increased pressure in the systemic arterial system. "In multivariable logistic regression analysis, IL-19 levels (95% CI, 20.1 to 62.9, P = 0.01) alone showed a significant positive association with DN even after adjusting for age, gender, hypertension, and blood fat." (PMID 28201997, 2017).
influenza (1 paper, 2022). An acute viral infection of the respiratory tract, occurring in isolated cases, in epidemics, or in pandemics; it is caused by serologically different strains of viruses (influenzaviruses) designated A, B, and C, has a 3-day incubation period, and usually lasts for 3 to 10 days. "Our findings indicate that IL-19 expression pattern in SARS-CoV-2 infection is distinct from that observed in conventional respiratory viral infections such as influenza or RSV infections." (PMID 36163397, 2022).
interstitial lung disease (1 paper, 2025). A diverse group of lung diseases that affect the lung parenchyma. "Other studies have also linked high IL19 expression to a poorer prognosis in interstitial lung disease among patients with SCLC." (PMID 40853920, 2025).
kidney injury (1 paper, 2024). Trauma to the kidney. "The results indicated that IL-19 was positively correlated with serum Cr level, a classic indicator of kidney injury." (PMID 38314821, 2024).
knee osteoarthritis (1 paper, 2025). "In another study, 50 g twice/day of freeze-dried strawberries for 12 weeks led to a reduction in TNF-α levels in obese adults with knee osteoarthritis, while IL-19 levels remained unchanged." (PMID 40944222, 2025).
liver disease (1 paper, 2021). "Despite the extensive role of IL-19 in various organs of the body, its role in liver diseases, especially in chronic liver diseases such as fatty liver and NASH, is completely unexplored." (PMID 34944021, 2021). "In conclusion, IL-19 may play an important role in the development of steatosis and fibrosis by directly regulating liver metabolism and may be a potential target for the treatment of liver diseases." (PMID 34944021, 2021). "In conclusion, this is the first report that IL-19 KO mice exacerbated NASH progression, IL-19 inhibited steatosis and fibrosis by directly regulating liver metabolism, and IL-19 plays an important role in liver disease." (PMID 34944021, 2021).
lower respiratory tract infection (1 paper, 2021). "SNPs in genes coding for interleukin (IL)-8, IL-19, IL-20, IL-13 mannose-binding lectin, interferon-gamma, and a regulated on activation, normal T cell expressed and secreted polymorphism have been associated with subsequent wheeze after RSV lower respiratory tract infection in term-born infants." (PMID 34386467, 2021).
Lymphadenopathy (1 paper, 2023). Enlargement (swelling) of a lymph node. "Furthermore, pretherapy IL-19 levels were significantly associated with lymphedema, general lymphadenopathy, and recurrence (r = 0.426, P < 0.001; r = 0.239, P = 0.035; r = 0.641, P < 0.001)." (PMID 36726488, 2023).
lymphedema (1 paper, 2023). Excess fluid collection in tissues, causing swelling. "Moreover, IL-19 levels had a significant correlation with lymphedema and recurrence." (PMID 36726488, 2023).
lymphoma (1 paper, 2023). A malignant (clonal) proliferation of B- lymphocytes or T- lymphocytes which involves the lymph nodes, bone marrow and/or extranodal sites. "Interestingly, an association between lung involvement and higher serum IL-19 levels was observed in lymphoma." (PMID 36726488, 2023). "Elevated IL-19 levels were observed in lymphoma patients and increased significantly in extranodal involvement (P < 0.001)." (PMID 36726488, 2023). "Patients with high levels of PD-L1/PD-1 coexpression with CXCR3 and IL-19 had inferior event-free survival (EFS) compared with that in lymphoma patients with low levels." (PMID 36726488, 2023). "The current study investigated PD-L1/PD-1 coexpression with CXCR3/CD36 in circulating lymphocytes, serum IL-19 levels, and their correlation with clinical outcome and extranodal involvement in lymphoma." (PMID 36726488, 2023). "Newly diagnosed 78 lymphoma patients had significantly higher IL-19 levels than normal volunteers (median = 237 vs. 7.2 pg/mL, P < 0.001)." (PMID 36726488, 2023). "Previous studies showed the association between high IL-19 levels and inferior clinical outcomes, assuming a major role for IL-19 in lymphoma progression." (PMID 36726488, 2023). "PD-L1+CXCR3+ lymphocytes and serum IL-19 might play a more important role in poor clinical behavior in lymphoma." (PMID 36726488, 2023). "In conclusion, PD-L1/PD-1 coexpression with CXCR3/CD36 and serum IL-19 may be involved in lymphoma extranodal involvement and have prognostic and predictive values in lymphoma." (PMID 36726488, 2023). "PD-L1/PD-1 coexpression with CXCR3/CD36 and IL-19 might play an inferior prognostic role in lymphoma, providing a new significant era in lymphoma immunotherapy, especially in patients with extranodal involvement." (PMID 36726488, 2023). "Coexpression of PD-L1/PD-1 with CXCR3/CD36 in circulating lymphocytes and serum IL-19 levels contributes to poor prognosis and might be potential markers for extranodal involvement in lymphoma." (PMID 36726488, 2023). "Posttherapy IL-19 levels were detected in lymphoma patients with extranodal involvement, and the median level was 628 pg/mL (range: 439-817.3), which was significantly higher than that of subjects without extranodal invasion with a median of 46.5 pg/mL (range: 33-137.5) (P < 0.001)." (PMID 36726488, 2023). "Furthermore, the study investigated the effect of this coexpression and IL-19 on lymphoma prognosis." (PMID 36726488, 2023). "Moreover, lymphoma patients had higher posttherapy IL-19 levels than the normal controls (median: 219 vs. 7, P < 0.001)." (PMID 36726488, 2023). "Compared to healthy controls, sera from lymphoma patients had a higher concentration of IL-19." (PMID 36726488, 2023). "Pretherapy IL-19 levels, CXCR3+%, and PD-L1+CXCR3+% in lymphoma patients with recurrence were statistically higher than in the PR patients (P < 0.001)." (PMID 36726488, 2023). "Interestingly, compared to patients without extranodal involvement, lymphoma patients with extranodal involvement had higher pretherapy IL-19 levels (median: 525 vs. 100, P < 0.001)." (PMID 36726488, 2023).
migraine (1 paper, 2022). "Furthermore, we identified genome-wide pleiotropy between migraine and lower levels of IL19, an anti-inflammatory cytokine that belongs to the IL10 cytokine subfamily." (PMID 35546551, 2022).
mouth ulcer (1 paper, 2021). "For example, IL-19 has three different SNPs in mouth ulcers, while LTA SNP polymorphism is significantly correlated to mouth ulcer." (PMID 34539639, 2021).
neuromyelitis optica (1 paper, 2021). A rare inflammatory disease of the central nervous system characterized mainly by attacks of uni- or bilateral optic neuritis (ON) and acute myelitis. "In fact, a recent study disclosed that serum IL-19 levels were lower in the relapse phase than the remission phase in patients with neuromyelitis optica." (PMID 33776998, 2021).
oral cancer (1 paper, 2013). "IL-19 specifically activated an intracellular signal and induced proliferation of the cells, which indicated that IL-19 may act in an autocrine manner in oral cancer." (PMID 24130695, 2013).
oral candidiasis (1 paper, 2022). Infection of the mucosal lining of the mouth with the fungus Candida albicans. "One understudied pathway that may be important for modulating oral candidiasis is the IL-20 cytokine signaling pathway that employs keratinocyte IL-20RB receptors as ligands for IL-19, IL-20, and IL-24." (PMID 36225230, 2022).
pancreatic cancer (1 paper, 2023). "We found that IL-19 most significantly increased the proportion of SP cells and the expression of stemness markers in pancreatic cancer cells in vitro, indicating that IL-19 plays a major role in promoting stemness in pancreatic cancer." (PMID 38098005, 2023). "Here, we verified the presence of IL-19 in the microenvironment of human pancreatic cancer by immunofluorescence staining." (PMID 38098005, 2023). "Similarly, IL-19 enhanced chemotherapy resistance in pancreatic cancer cells, and such an effect was reversed by Stattic." (PMID 38098005, 2023). "Notably, microenvironment-derived IL-19 serves as the primary ligand initiating the signaling cascade mediated by IL20RB in pancreatic cancer." (PMID 38098005, 2023). "Collectively, these findings suggested that microenvironment-derived IL-19 activates IL20RB-STAT3 pathway to promote the stemness and chemoresistance of pancreatic cancer cells." (PMID 38098005, 2023). "Immunofluorescence analysis confirmed the presence of IL-19 in the TME of clinical pancreatic cancer samples, which is consistent with findings in previous studies, suggesting the mechanism by which TME factors promote the stemness of pancreatic cancer cells." (PMID 38098005, 2023).
preeclampsia (1 paper, 2023). Preeclampsia is a hypertensive disorder of pregnancy that is characterized by new-onset hypertension with proteinuria presenting after 20 weeks of gestation, and depending on mild or severe forms may initially present with severe headache, visual disturbances, and hyperreflexia. "But it was interesting to note that the differences of both the allele and genotype frequencies of interleukin-19 polymorphisms and their contribution to the risk of preeclampsia susceptibility were significant." (PMID 38057745, 2023). "On the contrary, the present study revealed association of IL-19 gene polymorphisms in the preeclampsia group compared to the controls." (PMID 38057745, 2023). "This study was aimed to discover association between interleukin-13 (rs20541, and rs56035208) and interleukin-19 (rs1028181 (T/C) and rs2243191(T/C)) polymorphisms with susceptibility to preeclampsia." (PMID 38057745, 2023). "However, the interleukin-19 polymorphisms were found to confer the risk of preeclampsia in our population." (PMID 38057745, 2023).
Pruritus (1 paper, 2023). Pruritus is an itch or a sensation that makes a person want to scratch. "It was shown that the expression of genes encoding inflammatory mediators such as CCL4, CCL7, CCL8, CCL20, interleukin-19 (IL-19), IL-20, IL-26, IL-36A, IL-36G, and TNF-α) was unique to psoriatic skin with pruritus." (PMID 37834183, 2023).
psoriatic arthritis (1 paper, 2019). Joint inflammation associated with psoriasis. "Circulating IL-19 levels in patients with psoriatic arthritis were highly correlated with PASI scores (Spearman’s r = 0.66, p < 0.0001)." (PMID 30914699, 2019). "The inclusion of psoriatic arthritis patients and genital psoriasis patients provided an opportunity to evaluate IL-19 levels across a range of PASI scores, including patients with limited BSA (<10%)." (PMID 30914699, 2019). "Many patients with limited skin disease, including genital psoriasis and psoriatic arthritis patients, also had increased IL-19, which was reduced to normal levels upon ixekizumab treatment, correlating with PASI improvement." (PMID 30914699, 2019).
renal fibrosis (1 paper, 2020). A final common manifestation of a wide variety of chronic kidney diseases characterized by glomerulosclerosis and tubulointerstitial fibrosis. "However, since IL-19 and IL-20 signal through the same receptor complexes it is also possible that they exert similar effects on the scar tissue formation, therefore further experiments are needed to clarify their role in the process of renal fibrosis." (PMID 32306980, 2020).
Splenomegaly (1 paper, 2023). Abnormal increased size of the spleen. "Interestingly, pretherapy IL-19 was positively correlated with LDH levels (r = 0.349 and P = 0.002), hepatomegaly (r = 0.362 and P = 0.001), and splenomegaly (r = 0.231 and P = 0.042)." (PMID 36726488, 2023).
spondyloarthritis (1 paper, 2016). "We recently identified inverse correlations between plasma IL-19 levels and disease activity in patients with spondyloarthritis suggesting IL-19 and IL-20R1 have anti-inflammatory properties." (PMID 26968800, 2016).